PPP4R3A (protein phosphatase 4 regulatory subunit 3A)
Description:
Regulatory subunit of serine/threonine-protein phosphatase 4. May regulate the activity of PPP4C at centrosomal microtubule organizing centers. The PPP4C-PPP4R2-PPP4R3A PP4 complex specifically dephosphorylates H2AX phosphorylated on 'Ser-140' (gamma-H2AX) generated during DNA replication and required for DNA DSB repair.
Synonyms: KIAA2010; PP4R3A; SMEK1; MSTP033; FLJ20707; FLFL1; smk-1; smk1; PP4R3
Tractability: PROTAC: ubiquitination databases record sites on it.
Gene: Protein-coding gene on chromosome 14 (91,457,139 to 91,510,556, reverse strand). Ensembl gene ENSG00000100796.
Subcellular location: Cytoplasm; Cytoplasm, cytoskeleton, microtubule organizing center, centrosome; Nucleus
Subcellular location (Human Protein Atlas): Nucleoplasm; Cytosol; Nuclear speckles
Gene Ontology:
Molecular function: protein phosphatase activator activity; protein phosphatase regulator activity
Biological process: DNA damage response; regulation of double-strand break repair
Cellular component: cytosol; nuclear speck; nucleoplasm; protein phosphatase 4 complex; centrosome; cytoplasm; nucleus
Genetic constraint (gnomAD): Loss-of-function variants: 12 observed, 73.81 expected, observed/expected ratio (o/e) 0.16, 90% interval 0.1 to 0.26. The upper end of that interval is the gene's LOEUF score, 0.26, which puts it in group 1 of 6, group 1 being the genes least tolerant of losing a copy. Missense variants: 608 observed, 965.13 expected, observed/expected ratio (o/e) 0.63, 90% interval 0.59 to 0.67. Synonymous variants: 364 observed, 342.58 expected, observed/expected ratio (o/e) 1.06, 90% interval 0.97 to 1.16.
Homologues: Orthologues: pig PPP4R3A (99% identical), rabbit PPP4R3A (99% identical), rat Ppp4r3a (99% identical), macaque PPP4R3A (98% identical), mouse Ppp4r3a (98% identical), chimpanzee PPP4R3A (94% identical), zebrafish smek1 (87% identical), guinea pig PPP4R3A (87% identical), chimpanzee SMEK1 (59% identical), Drosophila melanogaster flfl (55% identical), Caenorhabditis elegans smk-1 (38% identical). Paralogues in human: PPP4R3B (73% identical), PPP4R3C (52% identical).
Diseases named in the same sentence as PPP4R3A in open-access papers:
PPP4R3A is named in the same sentence as 27 diseases in open-access papers, as found by Europe PMC text mining. Sharing a sentence is not in itself a finding about the gene and the disease. The quoted sentences say what the papers report.
Anxiety (1 paper, 2022). Intense feelings of nervousness, tension, or panic often arise in response to interpersonal stresses. "In summary, our results demonstrate that loss of PPP4R3A in the cortex and hippocampus led to elevated anxiety- and depression-like behaviors in mice." (PMID 35314861, 2022). "Selective knockout of Ppp4r3a in the cortex and hippocampus mimicked the depression- and anxiety-like behavioral effects of chronic stress in mice." (PMID 35314861, 2022). "Furthermore, mice with Ppp4r3a deficiency in the cortex and hippocampus mimicked CUMS-induced depression- and anxiety-like behaviors." (PMID 35314861, 2022).
depression (1 paper, 2022). "Herein, we provide direct evidence that Ppp4r3a deficiency impairs synaptic protein synthesis and synaptogenesis and consequently results in depression-like behaviors by inhibiting the mTORC1 cascade." (PMID 35314861, 2022). "After 28 days of CUMS, Ppp4r3a-OE mice showed resistance to CUMS-induced depression-like behaviors compared with control mice, as confirmed by normal sucrose preference in the SPT and normal immobile time in the FST or TST." (PMID 35314861, 2022). "The overexpression of Ppp4r3a in mice attenuated downregulation of mTORC1 and disrupted synaptic protein synthesis, thus leading to relief in depression-like behaviors." (PMID 35314861, 2022). "PPP4R3A is involved in chronic stress-induced depression and is a promising biomarker and therapeutic target for depressive disorder." (PMID 35314861, 2022). "Together, our findings suggest a significant role of PPP4R3A in driving synaptic protein synthesis and in resisting depression-like behaviors in chronic stress by activating the mTORC1 cascade." (PMID 35314861, 2022). "In the present study, we noticed reduced expression of PPP4R3A in CUMS-exposed depression-like mice." (PMID 35314861, 2022). "Together, these findings suggest prospects for Ppp4r3a in depression therapy." (PMID 35314861, 2022). "Importantly, we endeavored to reveal the role of Ppp4r3a in chronic stress-induced depression and to find the bridge by which Ppp4r3a regulates the synthesis of synaptic proteins." (PMID 35314861, 2022). "To determine whether Ppp4r3a is involved in depression and is related to the synthesis of synaptic proteins, we analyzed the behavioral effects and synaptic basis in Ppp4r3a-knockout and -overexpressing (OE) mice." (PMID 35314861, 2022). "The overexpression of Ppp4r3a in the cortex and hippocampus of mice rescued CUMS-induced depression-like behaviors, indicating that Ppp4r3a is a protective factor under chronic stress." (PMID 35314861, 2022). "In our study, in CUMS-exposed depressive mice, diminished expression of PPP4R3A was observed in the PFC and hippocampus, suggesting the involvement of Ppp4r3a in the development of depression." (PMID 35314861, 2022). "Thus, our data demonstrate reduced expression of PPP4R3A in CUMS-exposed mice, suggesting its possible involvement in the development of depression-like behaviors in mice." (PMID 35314861, 2022).
leukemia (1 paper, 2017). A malignant (clonal) hematologic disorder, involving hematopoietic stem cells and characterized by the presence of primitive or atypical myeloid or lymphoid cells in the bone marrow and the blood. "Additionally, qRT-PCR analyses of the other PPP4 regulatory subunits Ppp4r1, Ppp4r3a, and Ppp4r3b were performed to validate specific knockdown of Ppp4r2 in the MLLT3-KMT2A leukemia model." (PMID 29221109, 2017).
thyroid cancer (1 paper, 2024). "Subsequently, a series of functional experiments were conducted to investigate the impact of PPP4R3A and its Asp409Asn missense variant in thyroid cancer." (PMID 38275415, 2024). "Subsequently, we performed functional studies to investigate the impact of PPP4R3A and its missense variant Asp409Asn in thyroid cancer." (PMID 38275415, 2024). "In our study, we investigated for the first time the role of PPP4R3A in thyroid cancer progression and its underlying mechanisms." (PMID 38275415, 2024). "To elucidate the mechanisms underlying the tumor-suppressive effect of PPP4R3A in thyroid cancer, we conducted transcriptome sequencing to identify the downstream pathways regulated by PPP4R3A." (PMID 38275415, 2024). "By combining pathogenicity prediction of mutations and the functional research progress of each gene, we ultimately focused on a novel missense mutation in the PPP4R3A gene and confirmed its association with the pathogenicity of thyroid cancer through subsequent functional assays." (PMID 38275415, 2024). "Further research is necessary to ascertain the presence of this variant in additional FNMTC pedigrees and elucidate the downstream mechanisms involving PPP4R3A in thyroid cancer." (PMID 38275415, 2024). "Initially, we conducted knockdown experiments targeting PPP4R3A to preliminarily validate its role as a tumor-suppressor gene or oncogene in thyroid cancer." (PMID 38275415, 2024). "Given the crucial role of the PI3K/Akt/mTOR pathway in the occurrence and development of thyroid cancer, further investigation of the specific downstream mechanisms by which PPP4R3A regulates the activity of this axis is of great significance." (PMID 38275415, 2024). "Considering the significance of the PI3K/Akt pathway in FNMTC progression and its potential relationship with invasiveness, we hypothesize that PPP4R3A regulates thyroid cancer development through this pathway." (PMID 38275415, 2024). "Knockdown of PPP4R3A in vitro enhanced the proliferation, migration, and invasion abilities of normal thyroid cells and PTC cells, while its overexpression had the opposite effects, suggesting PPP4R3A as an important suppressor of thyroid cancer progression and metastasis." (PMID 38275415, 2024). "Finally, we were particularly intrigued by the gene PPP4R3A, which has shown high pathogenicity prediction scores and has been reported in various malignancies in recent years but has not been studied in thyroid cancer before." (PMID 38275415, 2024).
tumor (8 papers, 2014 to 2024). "However, overexpression of the PPP4R3A Asp409Asn mutant resulted in loss of tumor-suppressive function, ineffective inhibition of cell invasion, and even promotion of cell proliferation and migration by activating the Akt/mTOR signaling pathway." (PMID 38275415, 2024). "However, the p.Asp409Asn mutation in PPP4R3A not only eliminates its tumor-suppressive function but also promotes the activation of the Akt-mTOR-S6K/4E-BP pathway, thereby enhancing cell proliferation." (PMID 38275415, 2024). "Collectively, these functional experimental results indicate that PPP4R3A exhibits tumor suppressor functions." (PMID 38275415, 2024). "Our findings demonstrated that wild-type PPP4R3A exerted tumor-suppressive effects via the Akt-mTOR-P70 S6K/4E-BP1 axis." (PMID 38275415, 2024). "In addition, PPP4R3A plays an important role in the maintenance of embryonic stem cell pluripotency, hepatic gluconeogenesis, glucose metabolism, tumor suppression, tumor angiogenesis, microRNA biogenesis and transcription initiation." (PMID 35314861, 2022).
cancer (6 papers, 2014 to 2024). A tumor composed of atypical neoplastic, often pleomorphic cells that invade other tissues. "KEGG pathway analysis of the DEGs demonstrated a close association between PPP4R3A and cancer signaling pathways, particularly PI3K/Akt." (PMID 38275415, 2024).
PPP4R3A also shares sentences with these, for which no sentence is quoted: ovarian carcinoma (5 papers); ovarian tumor (2); Alzheimer disease (1); amyloid (1); atherosclerosis (1); autoimmune disorders (1); cervical tumor (1); cognitive decline (1); colon cancer (1); dementia (1); diabetes (1); experimental autoimmune encephalomyelitis (1); Gliosis (1); hepatocellular carcinoma (1); infection (1); invasive carcinoma (1); metabolic disease (1); mild cognitive impairment (1); Obesity (1); Parkinsonism (1); tauopathies (1).